EMILIN2 (elastin microfibril interfacer 2)
Diseases named in the same sentence as EMILIN2 in open-access papers (continued):
Sharing a sentence is not in itself a finding about the gene and the disease.
scleroderma (1 paper, 2024). Scleroderma is a rare autoimmune connective tissue disorder characterized by abnormal hardening of the skin and, sometimes, other organs. "Immunofluorescence analysis revealed increased EMILIN-2 deposition in fibrotic lesions from scleroderma patients." (PMID 39639116, 2024). "Our data show that EMILIN-2 is upregulated in fibrotic lesions from scleroderma patients as well as upon bleomycin injection into murine skin." (PMID 39639116, 2024).
skin cutaneous melanoma (1 paper, 2021). "To this end, we queried the skin cutaneous melanoma (Firehose Legacy) TCGA cohort and drew the methylation landscape of the EMILIN2 gene using MEXPRESS." (PMID 34299131, 2021).
tumor (19 papers, 2010 to 2024). "In preclinical settings, loss of EMILIN-2 associated with an increased number of tumor lesions upon AOM/DSS treatment." (PMID 35148799, 2022). "EMILIN-2 expression is often down-regulated during tumor progression, however the impact of this loss has not been explored thus far." (PMID 35148799, 2022). "The strengths of our study are the detailed analysis of the association of EMILIN2 in tumor immunity, the molecular typing of ccRCC, and the development of a 6-gene prognostic model with a high AUC value." (PMID 36544490, 2022). "Although large body of evidence indicates that EMILIN2 is associated with tumor immunity and angiogenesis in various cancers, the role of EMILIN2 in ccRCC remains elusive." (PMID 36544490, 2022). "Our previous investigations indicate that low levels of EMILIN-2 are associated with exacerbated tumor progression, since, as mentioned, EMILIN-2 exerts tumor suppressive functions overall." (PMID 34299131, 2021). "We discovered that the expression of EMILIN2 inversely correlates with the efficacy of anti-PD-L1 treatment, additionally underlying the importance of the tumor microenvironment in this context." (PMID 34299131, 2021). "This indicates that EMILIN2 expression is significantly associated with tumor immunity." (PMID 36544490, 2022). "These novel results indicate that EMILIN-2 is a key regulator of the tumor-associated inflammatory environment and may represent a promising prognostic biomarker for CRC patients." (PMID 35148799, 2022). "Thus, for these patients we compared the tumor-associated EMILIN-2 expression levels with the blood count." (PMID 35148799, 2022). "Taken together, these results suggested that EMILIN-2 could be implicated in the regulation of PD-L1 expression by tumor cells and may be exploited to predict the response to immunotherapy." (PMID 34299131, 2021). "Taken together, the results provided in this study suggest that patients characterized by a highly methylated EMILIN2 gene may display poorly efficient vasculature that may be associated with reduced drug delivery to the tumor, and, on the other hand, by an increased immune-suppressive TME." (PMID 34299131, 2021). "Consistently, ablation of EMILIN-2 associated with a higher infiltration of MDSC cells, negative regulators of the tumor immunosurveillance." (PMID 35148799, 2022). "The prevalence of M2 macrophages in the tumor tissues from Emilin-2−/− mice was consistent with a 100% increase of IL-10, one of the main M2-associated cytokines." (PMID 35148799, 2022). "In the tumor microenvironment, EMILIN-2 affects the activation of the Wnt/β-catenin signaling pathway, a key regulator of CRC development, thus down-modulating cell proliferation and migration." (PMID 35148799, 2022). "In fact, low EMILIN-2 levels correlated with a low M1/M2 macrophage ratio infiltrating the tumor tissue, and with poor CRC patient prognosis." (PMID 35148799, 2022). "In agreement with an exacerbated CRC development, the tumor immune infiltrate in Emilin-2−/− mice was characterized by an imbalance of the M1/M2 ratio, the polarization tilting towards the M1 phenotype." (PMID 35148799, 2022). "In order to study the relationship between ELIMIN2 expression and tumor stage, we analyzed the EMILIN2 expression in ccRCC patients using TNM stage information." (PMID 36544490, 2022). "The tumor burden was comparable between the two mouse models, even if the Emilin-2−/− mice were characterized by a slightly increased number of lesions with a diameter higher than 0.3 cm, despite the differences were not significant." (PMID 35148799, 2022). "The ccRCC samples (cancer tissues and adjacent tumor samples) were divided into high and low expression groups according to the median expression of EMILIN2." (PMID 36544490, 2022). "The results showed that the EMILIN2 expression was significantly different in different tumor pathological stages." (PMID 36544490, 2022).
tumor (continued). "EMILIN-2 exerts a suppressive function in a number of tumor types and its expression is often down-regulated during tumor progression." (PMID 34299131, 2021). "Here, we investigated the putative role of the ECM molecule EMILIN-2, a tumor suppressive and pro-angiogenic molecule." (PMID 34299131, 2021). "We envision that, due to the multiple roles exerted by EMILIN-2 in the tumor microenvironment, the molecule has potential value as a good biomarker to predict the efficacy of PD-L1 blockade strategies." (PMID 34299131, 2021). "Other few proteins such as Fibulin-2, EMILIN-2, and Decorin, are described also to have tumor suppressive functions." (PMID 34299025, 2021). "Surprisingly, the over-expression of this matricellular protein in tumor xenografts led to the discovery of the pro-angiogenic function of EMILIN-2." (PMID 32456248, 2020). "In fact, while some of the tumor samples were characterized by EMILIN-2 levels comparable to those of the normal tissue, other patients displayed a major decrease of EMILIN-2 expression." (PMID 30544909, 2018). "In particular, we analyzed the expression of Multimerin-2 a glycoprotein expressed by endothelial cells displaying angiostatic functions and EMILIN-2, known to affect tumor growth both directly and indirectly impinging on angiogenesis." (PMID 30544909, 2018). "At the functional level, EMILIN2 significantly impairs the growth of a number of tumor types inducing tumor cell apoptotic death and impairing Wnt signaling." (PMID 27809279, 2016). "Five genes (62.5%) demonstrated tumour acquired methylation (EMILIN2, SALL1, DBC1, FBLN2 and CIDE-A), whilst the remaining 3 (COMP, EPSTI1, SIM2) showed equal methylation in the corresponding normal breast tissue DNA." (PMID 20205715, 2010). "Next, we hypothesized that the increased number of tumor lesions observed in Emilin-2−/− mice could be accounted for the escape of tumor cells from immunosurveillance." (PMID 35148799, 2022). "Taken together these results pinpoint EMILIN-2 as an important regulator of the tumor inflammatory microenvironment and suggest that EMILIN-2 could represent a promising prognostic marker for CRC patients." (PMID 35148799, 2022). "EMILIN-2 acts as a tumor suppressor in different cancer types and the finding that the molecule was down-regulated in CRC patients prompted us to hypothesize that it could play a crucial role in this context." (PMID 35148799, 2022). "On the contrary, the tumor tissues were characterized by a strong reduction of the EMILIN-2 levels." (PMID 35148799, 2022). "This may explain why the Emilin-2−/− mice displayed a higher number of tumor lesions despite the rich macrophage infiltrate." (PMID 35148799, 2022). "Meanwhile, EMILIN2 expression is closely related to tumor immune infiltration in ccRCC." (PMID 36544490, 2022). "In addition, we analyzed the EMILIN2 expression in paired ccRCC and adjacent normal tissues, and found that the EMILIN2 expression was significantly higher in tumor tissue samples." (PMID 36544490, 2022). "Notably, independent studies demonstrated that Emilin-2 plays a critical role in modulating tumor cell apoptosis and angiogenesis." (PMID 35012633, 2022). "This further highlights the complex regulations wielded by EMILIN-2, which may lead to different effects depending on the peculiar molecular characteristics of the tumor cells and/or the tumor microenvironment." (PMID 35148799, 2022). "Although EMILIN2 was shown to affect angiogenesis, further experimental investigation is needed to confirm whether it affects tumor immunity by regulating angiogenesis in ccRCC." (PMID 36544490, 2022). "Instead, in the late stages, lack of EMILIN-2 associated with a decreased number of M1 macrophages, resulting in a higher percentage of the tumor-promoting M2 macrophages." (PMID 35148799, 2022). "These evidences indicate that EMILIN2 is closely related to the tumor microenvironment." (PMID 36544490, 2022).
tumor (continued). "This resulted in increased number of tumor lesions, suggesting that a higher expression of EMILIN-2 in the tumors may suppress the recruitment of MDSC cells restraining the escape of transformed tumor cells and the formation of CRC lesions." (PMID 35148799, 2022). "This indicates that EMILIN2 expression affects the tumor microenvironment in ccRCC." (PMID 36544490, 2022). "Indeed, low levels of EMILIN-2 not only imply reduced tumor vascularization but also impaired vascular efficiency, which, in turn, leads to poor drug delivery within the tumors." (PMID 34299131, 2021). "In fact, the anti-tumoral activity exerted by EMILIN-2 during tumor progression may be overcome during treatment." (PMID 34299131, 2021). "Similarly, the EDEN protein EMILIN-2 modulates angiogenesis activating IL-8 expression and affects tumor growth via the modulation of different signaling pathways." (PMID 30544909, 2018). "Interestingly, the analyses of the tumor samples revealed that, while in some of the patients the levels of EMILIN-2 were comparable to the normal counterpart, in other patients the expression was dramatically decreased." (PMID 30544909, 2018). "In CRC, the switch of immune-stimulating M1 cells in favor of the immune-suppressive M2-like cells not only foster tumor growth and progression but also promotes resistance to therapy; this possibility suggests that the expression levels of EMILIN-2 may also affect the efficacy of CRC treatment." (PMID 35148799, 2022). "It must be pointed out that the tumor immune microenvironment is characterized by a remarkable complexity, thus a more comprehensive analysis was required to better define which parameters could better describe the relation between EMILIN-2 and macrophages." (PMID 35148799, 2022). "Furthermore, tumor vessels developed in EMILIN2-deprived microenvironments display a worsen integrity of the basal lamina suggesting that it might also affect vessel perfusion and drug delivery (unpublished observations)." (PMID 27809279, 2016). "EMILIN-2 is an ECM molecule belonging to the EDEN protein family and exerts a suppressive function in a number of tumor types." (PMID 35148799, 2022). "As with the EMILIN2-PDGFD fusion, it is difficult to determine with certainty if TNC-PDGFD plays a driving role in the transformation of this tumor from DFSP to fibrosarcomatous DFSP, but it is a possible candidate." (PMID 34256767, 2021). "The cognate protein EMILIN-2 exerts multiple functions in the TME overall, leading to tumor-suppressive effects." (PMID 32456248, 2020). "Although it was not possible to verify similar changes in CRC patients, our preclinical data indicated that in the early phases of CRC development EMILIN-2 up-regulates the expression of IL-12 and INF-γ, key cytokines supporting a tumor-prohibitive microenvironment." (PMID 35148799, 2022). "Two additional members of this family, Emilin1 and Emilin2, resulted enriched in their respective AAV9-pool, and scored high in the final ranking (33rd and 77th position, respectively), confirming a relevant role of these ECM proteins in inhibiting tumor invasiveness." (PMID 38195652, 2024). "Since the AOM/DSS treatment associated with an increased number of neoplastic lesions in Emilin-2−/− mice, we hypothesized that the lack of EMILIN-2 could lead to poor tumor immunosurveillance, leading to the escape of a higher number of transformed cells." (PMID 35148799, 2022). "As an important regulator in the tumor microenvironment, EMILIN-2 gene is methylated in a number of tumors, thus it is possible that patients displaying low EMILIN-2 expression may be characterized by high levels of EMILIN-2 gene methylation." (PMID 30544909, 2018).
cancer (11 papers, 2011 to 2025). A tumor composed of atypical neoplastic, often pleomorphic cells that invade other tissues. "In particular, EMILIN2 in LCNEC showed significant positive correlations with cancer-associated fibroblasts (CAFs), matrix, and matrix remodeling (Spearman's r values of 0.890, 0.842, and 0.596, respectively; P < 0.001)." (PMID 40230612, 2025). "EMILIN2 expression is strongly associated with cancer progression in ccRCC patients." (PMID 36544490, 2022). "To the effect of EMILIN2 on various cancer types, we analyzed the EMILIN2 expression in cancer tissues and adjacent tissues in 33 types of cancer using data from TCGA." (PMID 36544490, 2022). "We first analyzed the EMILIN2 expression in 33 cancer types and its ability to predict patient survival." (PMID 36544490, 2022). "ECM molecules like Fibulin-3, Tenascin-C and Emilin-2 have been known to associate with growth factor receptors like EGFR to regulate its activation and function during cancer progression." (PMID 32719793, 2020). "EMILIN2, which is a component of extracellular matrix, suppresses the growth of cancer cells and has a role in cell survival and apoptosis." (PMID 24165089, 2013). "EMILIN2 was found to have prognostic significance in five cancers." (PMID 36544490, 2022). "Concurrently, we analyzed the prognosis of EMILIN2 in these 33 cancers." (PMID 36544490, 2022). "EMILIN2 was found to be expressed differentially in various cancer types (p < 0.05)." (PMID 36544490, 2022). "It is also possible that the loss of EMILIN-2 may be due to increased degradation of the molecule, since the ECM remodeling is known to occur during cancer progression." (PMID 30544909, 2018). "EMILIN2 was identified in humans in plasma/serum, amniotic fluid, seminal plasma, stem cells, cancer cells, and heart stem cells suggesting EMILIN2 may play important physiological/pathological roles." (PMID 21569335, 2011). "QUE alone largely downregulated some genes with a role in promoting cancer (e.g., OLFML2B, EMILIN2, and CD36), which is consistent with the anticancer potential of this natural extract." (PMID 37755981, 2023).
adenocarcinoma (2 papers, 2022). A common cancer characterized by the presence of malignant glandular cells. "EMILIN2, which is thought to confer elasticity to tissues and modulate receptor signaling, was identified as downregulated in both SqCC and adenocarcinomas." (PMID 36404344, 2022). "Overall, our observations indicated that tumors developed in Emilin-2−/− mice were not only more frequent but were also characterized by histological features indicating a higher propensity to progress into adenocarcinomas." (PMID 35148799, 2022).
colon polyps (1 paper, 2022). "Furthermore, the MEXPRESS analyses indicated that a higher methylation of the EMILIN-2 gene was associated with higher rate of braf mutations (p = 0.040), higher number of colon polyps (p = 5.7e10− 6), increased lymphatic invasion (p = 0.040) as well as with the pathologic M status (p = 0.015)." (PMID 35148799, 2022).
GI tumors (1 paper, 2020). "Multimerin-2 and Elastin microfibril interfacer 2 (EMILIN-2) are two ECM proteins, both belonging to the EMI domain endowed (EDEN) family, that display key functions in angiogenesis and have been extensively studied in the context of GI tumors." (PMID 32456248, 2020).
heart disease (1 paper, 2015). "EMILIN2 is expressed during cardiovascular development, on cardiac stem cells, and in heart tissue in animal models of heart disease." (PMID 25658937, 2015).
infection (1 paper, 2023). The state of being infected such as from the introduction of a foreign agent such as serum, vaccine, antigenic substance or organism. "A further three non-infection associated genes (CYGB, IRF6 and elastin microfibril interfacer 2 (EMILIN2)) were assessed." (PMID 37276213, 2023).
inflammation (1 paper, 2022). Aberrant reaction of the microcirculation characterized by movement of fluid and leukocytes from the blood into extravascular tissues. "In order to determine if EMILIN-2 expression could be impaired not only during CRC growth, but also in the context of chronic inflammation, we interrogated a cohort of 363 patients affected by chronic intestinal inflammation (GEO ID: GSE83687)." (PMID 35148799, 2022).
EMILIN2 also shares sentences with these, for which no sentence is quoted: fibrosarcoma (2 papers); acute lymphocytic leukemia (1); adrenocortical carcinoma (1); bladder cancer (1); cardiovascular diseases (1); cognitive decline (1); colon adenocarcinoma (1); epithelial dysplasia (1); hearing loss (1); hemangioendothelioma (1); hepatocellular carcinoma (1); liver cancer (1); lymph node metastases (1); lymphocytic leukemia (1); myopia (1); non-small cell lung carcinoma (1); oral cancer (1); pancreatic cancer (1); porokeratosis of Mibelli (1); prostate carcinoma (1); prostate tumour (1); systemic sclerosis (1); testicular germ cell tumor (1); uveal melanoma (1).